BCL2 (BCL2 apoptosis regulator)
Diseases named in the same sentence as BCL2 in open-access papers (continued):
Sharing a sentence is not in itself a finding about the gene and the disease.
tumor (continued). "Tumor cells frequently overexpress anti-apoptotic BCL-2 proteins and have therefore become “BCL-2 addicted”30." (PMID 32839432, 2020). "The deletion of tumor suppressor genes microRNA-15 (miR-15) and microRNA-16 (miR-16) located in the 13q14 chromosome can also lead to increased expression of BCL2." (PMID 33292251, 2020). "In previous works, the ability of plant miRNAs16 to induce cell death by BCL2-mediated apoptosis in tumor cells has been demonstrated." (PMID 32550010, 2020). "Relative to normal saline treatment, exo-miR-375 agomir or exo-NC-agomir administration elevated E-cadherin expression, and decreased the expression of ENAH, Ki-67 and Bcl-2 in the tumor tissues, of which exo-miR-375 agomir led to more pronounced alterations." (PMID 32698859, 2020). "Higher expression of Bcl2 in cancercells is known to lead to tumor progression by preventing apoptosis (Florouet al., 2013)." (PMID 32745158, 2020). "The overexpression of Bcl-2 and/or Bcl-xL in tumor cells is commonly known to block the proceeding of apoptosis." (PMID 32392733, 2020). "Prior research revealed that JNK1 phosphorylates BCL2 to disrupt the interaction of Beclin‐1 and BCL2, which induces autophagy activation in tumor cells." (PMID 32592208, 2020). "IL-6 promotes tumor cell proliferation by acting through the STAT3 pathway to upregulate Myc expression and induces the expression of anti-apoptotic genes encoding bcl2, bcl-XL and survivin to promote tumor survival." (PMID 33076397, 2020). "Vitexin (2 mg/kg, i.p., 4w) also inhibited NSCLC tumor growth, increased the expression levels of Bax and cleaved caspase‐3, and decreased the expression of Bcl‐2 in the tumor tissue of mice (Liu, Jiang, Liu, & Luo, 2019)." (PMID 32566174, 2020). "First, they participate in apoptosis of tumor cells through pathways mediated by Bcl-2 and its upstream transcription factor p-CREB." (PMID 32284761, 2020). "BCL2 expression has been previously investigated in MB and it was found to be IHC positive in patients with tumor cell undifferentiation, aged less than three or more than fifteen years." (PMID 32365560, 2020). "Phosphorylated STAT3 increases tumor cell proliferation, migration, and invasion by increasing the expression of genes such as b-cell lymphoma 2 (Bcl2), cyclin D1, and c-myc." (PMID 32432040, 2020). "Quercetin reduced tumor incidence and induced apoptosis through the modulation of NF-ĸB signaling and its target genes Bcl-2 and Bax in the DMBA (7,12-dimethylbenz(a)anthracene)-induced carcinogenesis hamster model." (PMID 32486484, 2020). "Aberrant Stat3 activation stimulates tumor cell proliferation through inhibition of apoptosis, a function mediated by upregulation of the antiapoptotic gene Bcl-2." (PMID 32258099, 2020). "The decreases in tumor expression of Bcl-2 and Mcl-1 after DT2216 treatment were likely due to the activation of caspase-3 and induction of MyLa cell apoptosis." (PMID 32677976, 2020). "miR-15a/16 exerts tumor suppressive roles by targeting multiple oncogenes, including BCL2, TWIST1, MCL1, CCND1 and WNT3A." (PMID 32678069, 2020). "The B cell lymphoma-2 (BCL-2) family proteins play a key role in regulating intrinsic apoptosis and, in many cancers, are the main culprits behind tumor survival and therapy resistance." (PMID 32742874, 2020). "There is evidence that the anti-apoptotic action of BCL-2 is a downstream target of the Hh pathway, and acts to promote tumor cell survival." (PMID 31967981, 2020). "Our Western blot results also showed that the expression of Bcl2 was significantly up‐regulated in CFTR‐overexpressing U87‐inoculated tumours compared to the tumours injected with control U87 cells." (PMID 32463592, 2020). "Conversely, knockdown or therapeutic targeting of USP9X destabilizes MCL-1 and sensitizes tumor cells to BCL-2/BCL-xL inhibitors." (PMID 33308268, 2020).
tumor (continued). "The CRISPR‐dCas9 system was used to downregulate the expression of the Bcl2 gene and to promote Bax gene expression, which induced apoptosis of tumor cells." (PMID 33135339, 2020). "The protein levels of Bcl-2 and Mcl-1 in various types of tumor tissues were found to be frequently augmented at a higher ratio than the other anti-apoptotic proteins in the Bcl-2 family." (PMID 32260280, 2020). "Neutralizing antibodies to IL-4 have inhibited tumor growth in xenograft models by reducing expression of anti-apoptotic Bcl-xL and Bcl-2." (PMID 32512917, 2020). "The anti-apoptotic functions of BCL2 help tumor cells overcome apoptosis stimuli, such as radiation." (PMID 32650615, 2020). "Previously, miR-497 has been identified as a tumor inhibitor based on its effects on Bcl-w, an anti-apoptosis Bcl-2 protein that plays an essential part in cell survival." (PMID 33364236, 2020). "Western blotting analyses showed that protein expression of BRD4, c-Myc, Bcl-2 and cyclin D1, were significantly decreased in A1874-treated tumor tissues, where caspase-3 and PARP cleavage was detected." (PMID 32978368, 2020). "Although promising results were obtained in a subset of MM patients treated with venetoclax, this activity is restricted to tumor clones with high BCL-2:MCL-1 and BCL-2:BCL-xL expression ratios as well as reduced electron transport chain activity." (PMID 33308268, 2020). "Such resensitization of treatment resistant tissues, is particularly attributed to the ability of PDT to directly target and inactivate anti-apoptotic proteins (Bcl-2 and Bcl-xL), often over-expressed in treatment resistant tumor cells." (PMID 37425217, 2020). "Further studies revealed that these miRNAs function as tumor suppressors to induce apoptosis by repressing the B-cell lymphoma 2 (Bcl-2) gene, and inhibit the cell cycle by the repression of cyclin-related genes such as CCND1 and CCNE1." (PMID 32660045, 2020). "Over-expression of PBXIP1 (HPIP) has been shown to inhibit apoptosis by up-regulating BCL2, to promote tumor cell proliferation via activation of ER, and to mediate EMT by regulating mesenchymal genes such as N-cadherin and Vimentin." (PMID 33194730, 2020). "A significantly increased expression of CD206 at IT level (mean score: 0±0 for control vs 2.3±0.5 for bcl-2 overexpressing tumors, p=0.007) was observed in bcl-2 overexpressing tumor xenografts when compared with control ones." (PMID 32269145, 2020). "The heterogeneity in intensity within a case was visualized by plotting the BCL2 fluorescence intensity of individual tumor cells on a case-by-case basis." (PMID 32606309, 2020). "The IHC analysis of F4/80+ cells confirmed the macrophage depletion in bcl-2 overexpressing tumor bearing mice." (PMID 32269145, 2020). "Tumour cells can acquire resistance to apoptosis by downregulating proapoptotic proteins such as Bax or by upregulating antiapoptotic proteins such as Bcl-2." (PMID 32239160, 2020). "These miRNAs have been described to have a tumor-suppressor function, being able to repress the expression and activity of several oncogenes, including Bcl2 and Cyclin D1." (PMID 31952362, 2020). "Elevated Bax/Bcl-2 ratio levels has been proven to drive human cancer cells to apoptosis as well as reduce tumor aggressiveness." (PMID 32984059, 2020). "In general, the combination of specific BCL-2 inhibitors with other approved anti-cancer drugs repeatedly proved a successful strategy in various tumor models)." (PMID 32839432, 2020). "There was decreased Bcl-2 and Bcl-xl expression in mouse tumor tissues and increased expression of Bad and Bax." (PMID 32300551, 2020).
tumor (continued). "Recently, ABT-263 has been widely used as an orally bioavailable inhibitor of prosurvival BCL-2 proteins in many antitumor therapies by targeting tumor cell apoptosis and inhibiting cell proliferation." (PMID 33519480, 2020). "Increased WT1 score significantly associated higher Bcl2 and Ki67 labelling indices, increasing WHO tumor grade and tumor’s histopathologic type (p<0.05) showing staining pattern variability by tumor entity and cell type." (PMID 32856872, 2020). "In summary, HF hybrid micelle treatment increased the ratio of Bax/Bcl-2, enhanced the expression of Caspase-3, and accelerated the tumor apoptosis." (PMID 32252563, 2020). "In order to avoid this death-inducing signals, tumor cells are often selected for upregulation of antiapoptotic BCL-2 family members including BCL-2, BCL-xl, BCL-W, BFL-1, and MCL-1." (PMID 32190086, 2020). "The pro-GRP was known as a surrogate marker of BCL-2 amplification and its changes correlated with changes in tumor volume." (PMID 33381025, 2020). "In this scenario, it has been reported that bcl-2 plays a pivotal role in orchestrating the crosstalk between tumor and neovascular endothelial cells." (PMID 32269145, 2020). "A novel treatment principle was introduced by targeting B cell lymphoma 2 (BCL2) using the BH3 mimetics, which cause immediate apoptosis of tumor cells." (PMID 32025827, 2020). "Both BH3 mimetics exerted dose-dependent cytotoxic activity, which strongly connected to Bcl-2 and Mcl-1 expression in these tumor cells showing high expression of Bcl-2 or Mcl-1 on both RNA and protein levels." (PMID 33362794, 2020). "The protein levels of RAB22A and Bcl2 in tumor tissues were measured by immunohistochemistry staining." (PMID 32618144, 2020). "293T cells transfected with tumor-associated mutant BAD show decreased apoptosis induction and mutant BAD binds inefficiently to BCL-2 and BCL-XL." (PMID 32335811, 2020). "The effects of Betatrophin on Wnt and apoptosissignaling pathways was assessed by measuring the expression level ofWIF1 as a tumor suppressor gene by real-time PCR, and theexpression of Bcl2 protein by western blot analysis." (PMID 32745158, 2020). "In this study, we detected Bcl-2 and Bax protein expression; the results showed that GLTs promote tumour cell apoptosis." (PMID 33161828, 2020). "The up-regulation of caspase-3, Bax, and the down-regulation of Bcl-2 indicated that the drug induced the apoptosis of tumor cells." (PMID 32292350, 2020). "The present re-investigation using fluorescence in situ hybridization revealed an IGH-MYC translocation and a break in the BCL2 locus in the tumor cells." (PMID 33339535, 2020). "In the case of CLL, the overexpression BCL-2 leads to inappropriate cell survival, tumor formation, and diminished sensitivity to chemotherapy." (PMID 32742874, 2020). "We observed a significant increase of tumor volume in bcl-2 overexpressing tumor bearing mice, starting from 17 days after cell injection." (PMID 32269145, 2020). "Compared with normal cells, the tumor cells always show a decreased expression of the Bax/BCL2 ratio." (PMID 33123002, 2020). "In this manner, the oncogene c-MYC not only promotes tumor cell proliferation but also collaborates with the antiapoptotic factor BCl2 in escaping immune surveillance by nearby immune cells." (PMID 33168041, 2020). "The expression of Bcl-2 gene is connected with low-grade tumors and its inhibition of apoptosis is regarded as a common tumor genesis pathway." (PMID 33374329, 2020).
tumor (continued). "In our previous works, BCL2 protein expression in lymphoid and monocytoid tumor lines was inhibited by treatment with specific plant miRNAs16 and MOES31." (PMID 32550010, 2020). "Markers of apoptosis, involving cleaved-PARP, cleaved caspase-3, and Bax, were increased in tumor cells, whereas of Bcl-2 was decreased." (PMID 32903546, 2020). "The miR-148a was found to inhibit Bcl-2, leading to the activation of an intrinsic mitochondrial pathway and tumor apoptosis in CRC." (PMID 32731413, 2020). "Meanwhile, the combination caused the obvious changes in the expression level of antiapoptotic proteins (depressing XIAP, Bcl-2, and survivin) and apoptotic proteins (promoting Bak), which lead to the suppression of tumor growth." (PMID 32265690, 2020). "Bax protein serves as a hallmark of cell apoptosis and is inhibited by overexpressing Bcl‐2 protein in cancer cells, contributing to tumor development and inhibition of cell apoptosis." (PMID 33135339, 2020). "Most chemotherapeutic drugs initiate the intrinsic signal pathway of apoptosis to kill tumor cells, but it is easy for tumor cells with high level of Bcl‐2 to evade apoptotic signal pathway." (PMID 32346976, 2020). "MCPyV-positivity and basal BCL-2 expression can be determined from primary tumor biopsies with relative ease and are likely predictors of the success of this combination." (PMID 32093022, 2020). "First, although Eμmyc/EμBCL‐2 murine tumors and EBV‐positive BL cells both overexpress MYC and BCL‐2 proteins, they have very different phenotypes: Eμmyc/EμBCL‐2 tumor cells have a lymphomyeloid progenitor phenotype, whereas BL cells have a GC phenotype." (PMID 32623836, 2020). "We found similar trends in Bax and Bcl-2 MFI for tumor stage, tumor size, and lymph node involvement." (PMID 32901694, 2020). "It is evident that treatment with α-m-Dox/M inhibits tumor progression through S phase cell cycle arrest and promoting apoptosis via the Bcl-2/Bax pathway." (PMID 33116114, 2020). "The surveying of anti-apoptotic Bcl-2 proteins in different tumor types led to a focus on the members more frequently expressed: BCL2, Bcl-xL, and MCL1." (PMID 33396645, 2020). "We demonstrate that cancer-specific bcl-2 promotes an IL-1β-driven pathway supporting the recruitment of M2 polarized macrophages, as well as formation of a pro-tumor microenvironment." (PMID 32269145, 2020). "Studies have confirmed that a shift in the Bax/Bcl-2 ratio is an important factor contributing to the low apoptosis rate of tumor cells and that this ratio is targeted by various antitumor drugs." (PMID 32215033, 2020). "The most important member of this family is Bcl-2, a protein with anti-apoptotic effects that is generally increased in certain types of neoplasms, among which is HCC, giving them greater invasive ability and a lower response to treatments." (PMID 32947962, 2020). "Bcl-2 and Ki67 tumor markers were significantly diminished in the mouse groups that were CDP treated." (PMID 32793477, 2020). "It is an orally bioavailable selective inhibitor of BCL-2, an antiapoptotic protein whose overexpression is related to tumor cell survival and resistance to chemotherapeutics." (PMID 33265952, 2020). "Over-expression of anti-apoptotic proteins (e.g., Bcl-2, Mcl-1 or Bcl-xL) is observed in many human malignancies including NSCLC, and associated with tumor progression, poor prognosis and chemotherapy resistance." (PMID 32212793, 2020). "LINC02418 acted as a tumor driver by negatively regulating cell apoptosis through LINC02418/miR-34b-5p/BCL2 axis in CRC." (PMID 32973404, 2020). "Given their similar characteristics, Bax, p73, Casp-9 and Bcl-2 have been classified as biomarkers for promotion of tumor apoptosis (BPAs) in this study." (PMID 32993581, 2020). "In xenograft tumor tissues, irradiation-induced increase in Bax expression and decrease in Bcl-2 expression were enhanced by miR-219a-5p." (PMID 32364222, 2020).
tumor (continued). "The distribution of BCL-2 expression was mostly observed in the cytoplasm and shown to be significantly higher in the vehicle control treated tumor sections." (PMID 32929356, 2020). "Treatment of HL-60 cell xenografted mice with crocin inhibited the tumor weight, size, and Bcl-2 expression and increased Bax expression in these cells." (PMID 32405344, 2020). "Subsequent detailed examination of tumour samples revealed that the mRNA expression level of Bcl2 was significantly up‐regulated in CFTR‐overexpressing tumours." (PMID 32463592, 2020). "For instance, BCL-2 inhibitors synergized with tamoxifen or chemotherapy and decrease tumor growth in preclinical models with highly BCL-2 expressing ER-positive or triple negative breast tumors." (PMID 32722518, 2020). "Anti-tumor efficacy of Dox nanocarriers was compared with free Dox through qualitative analysis of pharmacodynamic markers (Bcl-2 and PARP; regulated by the apoptotic pathway), which showed little difference between the groups." (PMID 33134314, 2020). "Immunohistochemistry was used to detect the expression levels of HDAC1, cleaved caspase-3, Bcl-2 and Bax in H226 and H520 CDXs tumor cells." (PMID 32903420, 2020). "Tumor volume, blood vessel invasion, and levels of the cell proliferation markers Ki67 and c-Myc and the anti-apoptotic marker Bcl2 decreased in response to high-dose DEX." (PMID 32156004, 2020). "In terms of pathological diagnosis, the immunophenotype analysis showed that the stromal lymphocytes were positive for CD20, CD79a, and BCL-2, while the tumor cells were positive for BCL-10, NF-kB, p65 and PAX-5." (PMID 33585230, 2020). "It is well-studied that tumor cells can be resistant to apoptosis due to the over-expression of anti-apoptotic machinery (Bcl-2 rheostat) operating inside these cells allowing their survival and metastases." (PMID 37425217, 2020). "As our studies to assess BH3-mimetic responses used MPM cell lines, it was important to confirm that their expression pattern of BCL-2 proteins was reflected in patient tumour samples." (PMID 33298868, 2020). "Protein Bcl-2 plays a key role in the regulation of apoptosis in which an increasing Bax/Bcl-2 ratio enhances caspase-3 activity and subsequently induces apoptosis in tumor cells." (PMID 32204409, 2020). "In a first study, we developed a new therapeutic approach joining tumor specificity with a direct induction of apoptosis on the level of the Bcl-2 proteins." (PMID 32580291, 2020). "Disarib induced cancer cell death in a BCL2 dependent manner in different cancer cell lines and mouse tumor models when it was administered intraperitoneally." (PMID 32938954, 2020). "We also examined the proliferation marker PCNA and the pro-apoptotic protein Bcl-2 to assess the effects of C10 treatment on the proliferation and apoptosis of the tumor xenografts." (PMID 32427575, 2020). "Accordingly, strategies to neutralize the anti-apoptotic Bcl-2 proteins thereby restoring apoptosis and eliminating tumor stem cells have led to the development of BH3 mimetics as therapeutic agents." (PMID 33362794, 2020). "Further, part of the tumor cells coexpressed BCL-2 and BCL-6, which was rarely seen in primary testicular lymphoma." (PMID 32590786, 2020). "HMWp activated expression of caspase-8 and -9 enzymes, and pro-apoptotic Bax protein whilst inhibiting expression of tumor survivor protein, Bcl-2." (PMID 32832273, 2020). "We also found inhibition of P38 phosphorylation and reduced PCNA, Ki67 and BCL2 levels, suggesting that the anti-inflammatory effects of GP inhibits P38, acting as an upstream regulator to inhibit proliferation and reduce tumor cell survival." (PMID 32630288, 2020).